WNT5A (Wnt family member 5A)
Diseases named in the same sentence as WNT5A in open-access papers (continued):
Sharing a sentence is not in itself a finding about the gene and the disease.
tumor (continued). "To date, the role of WNT5A is controversially disputed as it has been attributed to tumor-suppressive functions but also associated with negative outcomes." (PMID 29930766, 2018). "Expression of Wnt5a has been reported in several types of cancers, but the role of Wnt5a in the pathogenic mechanisms of cancer is still unclear, with opposing roles as tumor promoter and tumor suppressor being described." (PMID 28427201, 2017). "Studies have proposed both pro- and anti-tumor functions for WNT-5A and have identified several underlying signaling cascades." (PMID 26514730, 2016). "Several studies indicate an association of Ror2, in some cases downstream of Wnt5a, with tumor invasiveness and metastasis." (PMID 26680417, 2015). "We further examined the roles of WNT5A in several major signaling pathways underlying tumor progression, including PKC, ERK, AKT, and JNK pathways." (PMID 25823923, 2015). "Wnt5a activates the Wnt/β-catenin-independent pathway and its overexpression is associated with tumor aggressiveness enhancing invasive activity." (PMID 25622531, 2015). "Overexpression of Wnt5a has been demonstrated not only in tumor cells, but also in the tumor stroma, particularly tumor-associated macrophages." (PMID 24944588, 2014). "We previously showed that loss of Wnt5a in MMTV-PyVmT tumors resulted in a switch in tumor phenotype resulting in tumors with increased basal phenotype and high Wnt/β-catenin signaling." (PMID 25401739, 2014). "Previous data from our laboratory demonstrated that loss of Wnt5a in tumors induced by MMTV-PyVmT resulted in increased tumor growth, redirection of the tumor phenotype to a more basal-like subtype, and increased Wnt/β-catenin signaling." (PMID 25401739, 2014). "Methylation of SFRP4, WIF1 and WNT5a genes were meaningfully associated with increasing tumor stage (p = 0.004, p = 0.029 and p = 0.004)." (PMID 25107489, 2014). "In cancer, Wnt-5a is often dysregulated and the protein has been implicated both in tumor suppressive as well as in tumor promoting activities." (PMID 23990917, 2013). "Further studies are also needed to clarify the underlying mechanisms connecting Wnt5a and different tumor behavior." (PMID 23947922, 2013). "Further studies to investigate association between Wnt5a expression, tumor behavior and clinical outcome are necessary to fully validate the utility of Wnt5a for early diagnosis/prognosis of UC." (PMID 23947922, 2013). "The correlation of Wnt5a protein expression in UC tissue sections with histological grade and pathological stage of the tumor suggests its possible use as diagnostic/prognostic tool for UC." (PMID 23947922, 2013). "Taken together with the present clinical data these findings suggest that the absence or low expression of Wnt-5a in ER+ tumors can cause a more aggressive phenotype by increasing tumor cell invasiveness." (PMID 23990917, 2013). "For example, WNT5A can induce MMP expression in tumor-associated macrophages thereby promoting invasion." (PMID 23484019, 2013). "We, and others, have previously shown that loss or low expression of Wnt-5a in the primary tumor has an unfavorable prognostic value in breast, prostate and colon cancer." (PMID 23990917, 2013). "Among WNT signaling components implicated in oncogenesis, WNT5A is particularly interesting: it acts both as an oncoprotein and a tumor suppressor." (PMID 24260410, 2013). "Loss of Wnt5a staining in hepatocellular carcinoma was significantly associated with higher tumor stage." (PMID 23342259, 2012). "Methylation of Wnt5a is associated with distinct tumour subtypes, strengthening the evidence of an epigenetic-mediated Wnt bias in CRC." (PMID 21587258, 2011). "In CRC, Wnt5a expression has been associated with favourable outcome in early stage tumours, while loss of Wnt5a expression is a hallmark of CRC-derived liver metastases." (PMID 21587258, 2011). "Together, the data demonstrate that alterations in TGF-β signalling or loss of Wnt5a enhance tumour growth." (PMID 19344510, 2009).
tumor (continued). "With targeting will come a need to screen patients and their tumours for involvement of Wnt-5a and its associated signalling partners before chemotherapy to identify those most likely to benefit." (PMID 19603030, 2009). "Downregulation of Wnt-5a has been associated with higher tumour grade and was shown to be an independent factor indicating poor prognosis in a number of different tumour subtypes." (PMID 19603030, 2009). "The key findings here are that: TGF-β and Wnt5a regulate Wnt/β-catenin activity; and loss of TGF-β and Wnt5a redirect the phenotype of tumours so that they resemble tumours induced by activation of Wnt/β-catenin." (PMID 19344510, 2009). "Together the results suggest that loss of TGF-β or Wnt5a can redirect the phenotype of MMTVPyVmT tumours to a phenotype consistent with activated Wnt/β-catenin." (PMID 19344510, 2009). "Interestingly, although often downregulated, higher Wnt5A expression has been linked to improved prognosis, indicating a possible tumor-suppressive function in certain contexts." (PMID 40943055, 2025). "Similarly, tumor-associated macrophages (TAMs) can secrete Wnt5a to act as cellular sources of Wnt ligands for FZD signaling." (PMID 40376615, 2025). "The involvement of WNT5A signaling in cancer stem cell self-renewal, which is potentially associated with tumor initiation and metastasis, suggests that RUNX3 may cooperate with WNT5A to regulate cancer stem property." (PMID 38240752, 2024). "Proteins associated with tumor progression or a bad prognosis such as WNT5A, MMP13, MMP3, telomerase, and NOTCH3 were upregulated while proteins associated with immune cell infiltration or pathway inhibitors/tumor suppressors such as FRZB, CD177, PPARG, and HRASLS2 were downregulated." (PMID 38504345, 2024). "In addition, we discovered that cluster 2 is highly associated with some tumor stemness-related transcription factors: WNT5A, WNT10A, GATA2, and FOSL2." (PMID 38339238, 2024). "In ACC, Wnt5A overexpression was positively correlated with microsatellite instability and tumor mutational load, suggesting that it may be a prognostic marker for immunosuppressive checkpoints." (PMID 38269250, 2023). "Our published studies and other reports showed that Wnt5A exhibits a tumor-promoting effect and could be associated with EMT in EOC progression." (PMID 35053353, 2022). "Based on these findings, we hypothesized that deletion of GCTB-OCs by denosumab might decrease the level of sFRP in tumor tissues, activate a cascade of Wnt-5a/Ror2/Rac1 signaling, and finally cause the osteoblastic differentiation of GCTB-SCs." (PMID 35927428, 2022). "Moreover, it has been demonstrated that Wnt5a is an auto and paracrine molecule that stimulates oncogenic and tumor suppressor signaling associated with cancer type." (PMID 34603445, 2021). "In recent years, Wnt5a signaling in CAFs has been implicated in tumor progression." (PMID 33854601, 2021). "Moreover, transcript levels of genes associated with CRC susceptibility loci (e.g., Grem1 and Bmp4) and tumor development and invasion (e.g., Wnt5a, Ereg, Mmp3, Mmp13, Timp1, Saa3, Ptgs2, and Acsl4) were elevated in IL-11+ fibroblasts." (PMID 33863879, 2021). "For instance, some GC cell lines show low WNT5A levels, while cancer-associated fibroblasts (CAFs) or tumor-associated macrophages (TAMs) might secrete Wnt5a in the context of GC." (PMID 33869179, 2021). "In one research, CD163 positive tumor-associated macrophages (TAM) may induce angiogenesis via crosstalk with malignant epithelial cells to promote Wnt5a expression." (PMID 33754039, 2021). "Wnt5a might also be secreted by tumor-associated macrophages (TAMs), which are observed in GC and correlate with poor prognosis (Räihä and Puolakkainen, 2018)." (PMID 32195251, 2020). "Furthermore, EZH2 has been linked to epigenetic inactivation of WNT5A, a proposed tumor suppressor, during TGF-ß-induced epithelial-mesenchymal transition in an in vitro model of CRC." (PMID 31864341, 2019).
tumor (continued). "Intriguingly, although WNT5A has been generally found to be upregulated in PCa, its role is still unclear, as some studies report association with good prognosis 37, 38 whereas other report associations with tumor aggressiveness and poor prognosis 39-41." (PMID 31762801, 2019). "Tumor-derived exosomes also cause increased Wnt5a expression in macrophages." (PMID 28659795, 2017). "As activated WNT/β-catenin is associated with CRC, ectopic expression of WNT5A resulted in substantial inhibition of tumor cell clonogenicity of CRC cells, with downregulation of intracellular β-catenin protein level and concomitant decrease in β-catenin activity." (PMID 26514730, 2016). "Indeed, WNT-5A heterozygous mice develop spontaneous B cell malignancies underlining the tumor suppressive role of WNT-5A." (PMID 26514730, 2016). "Therapeutic approaches targeting Wnt5A may reduce microvascular leakage and subsequent edema formation associated with IL-4 driven pathophysiological conditions such as allergic and tumor inflammation." (PMID 27214384, 2016). "Furthermore, low Wnt5a expression was correlated with both tumor stage and overall survival, suggesting that loss of Wnt5a is predictive of poor outcome." (PMID 27571105, 2016). "On the contrary, Wnt5a was associated with tumor regional invasion." (PMID 26608372, 2016). "While IFN-γ is a rapid inducer of IDO expression in many cell types, studies are now demonstrating that the loss of TβRIII in a TGF-βhi tumor microenvironment promotes durable IDO expression by pDCs while the upregulation of the Wnt5a oncogene results in durable IDO expression by mDC populations." (PMID 25339948, 2014). "However, wnt5a has also been associated with a good prognosis or tumor suppression by inhibiting the wnt/β-catenin pathway in CRC." (PMID 24564183, 2014). "Certain studies have clarified the association between Wnt5a and tumor metastasis from the aspects of cell polarization and directional movements, since a shared feature of a number of noncanonical Wnt pathways is the targeting of the cytoskeleton, with important implications for cancer metastasis." (PMID 24944588, 2014). "Wnt5a expression tended to be negatively associated with tumor histological grade (P < 0.001)." (PMID 24156409, 2013). "Wnt5a was predominantly expressed on tumor margins in SCC (as well as in tumor associated stroma)." (PMID 22384081, 2012). "Notably, however, Wnt5a methylation increased with grade in both populations and trended towards an association with increasing tumour stage and, more specifically, pathological T substage in Newfoundland." (PMID 21587258, 2011). "On the other hand, oncogenic roles have been identified in prostate cancer, where Wnt5a promotes cell motility, melanoma, where expression associates with tumour invasion, and hepatocellular carcinoma, where expression is associated with poorly differentiated and invasive cell lines." (PMID 21587258, 2011). "Consequently, Wnt5a appears to be preferentially methylated among sporadic MSI tumours compared with HNPCC-associated MSI tumours." (PMID 21587258, 2011). "Although there are still arguments whether it is a tumor suppressor or promoter, Wnt5A overexpression has been found to be associated with aggressive tumor biology and poor prognosis." (PMID 20828404, 2010). "In addition, loss of TGF-β or Wnt5a signalling results in increased Sca1 expression and redirection of tumour phenotype to that consistent with excess Wnt/β-catenin signalling, including an increase in K6- and K14-positive cell populations." (PMID 19344510, 2009). "Thus, the data suggest that loss of Wnt5a results in increased canonical Wnt/β-catenin signaling in MMTV-PyVmT tumours." (PMID 19344510, 2009). "In addition, downregulation of Wnt5a is associated with a higher tumor grade of CRC patients." (PMID 28859077, 2017).
tumor (continued). "Similarly, Wnt5a and Wnt2 were found to be significantly up-regulated in colon cancer associated macrophages, illustrating that Wnt signals can originate from outside the tumour cells themselves." (PMID 27196929, 2016). "Indeed, treatments that could restore the effects of the tumor suppressive WNT5A isoform or block that of the oncogenic variant may confer clinical benefit in cancers in which alterations of these isoforms are implicated." (PMID 24260410, 2013). "Wnt5a-related tumor invasion may also be mediated by tumor-associated cells." (PMID 22384081, 2012). "Analogous arrangements were observed in BCC, with Wnt5a being most strongly expressed at the leading edge, as well as in tumor-associated stroma, while Fzd3 showed polarised expression within the tumor (top middle), or in Fzd3-positive nests (white arrow heads)." (PMID 22384081, 2012). "However, Fzd5 may mediate inflammatory responses triggered by Wnt5a secreted by tumor-associated stroma or endothelial cells such as inflammatory cytokine production." (PMID 22384081, 2012). "Importantly, this event was unequally distributed among MSI subtypes; Wnt5a methylation was much more common in MSI tumours than in MSS tumours in both populations and these associations were independent of the combined effects of patient age, sex, and tumour location." (PMID 21587258, 2011). "Wnt5a is ubiquitously expressed in normal tissues, but is often dysregulated in tumours and has been controversially implicated in both tumour suppression and oncogenesis in addition to being recognised asa marker of both favourable and poor outcome in primary cancer." (PMID 21587258, 2011). "Plasma Wnt5a levels also correlated with tumor size and pancreatic islet β-catenin expression in patients with PDAC." (PMID 41593307, 2026). "In the present study, α‐MEL‐RES treatment significantly reduced the protein expressions of Wn3a, Wnt5a, and β‐catenin in GB cells and in the tumor tissues of HS683 tumor‐bearing mice, indicating that α‐MEL‐RES suppressed GB." (PMID 40400263, 2025). "The interplay between canonical and non-canonical pathways is particularly complex, as ligands like Wnt5a can activate both, with context-dependent effects on tumor progression." (PMID 40376615, 2025). "As most of the studies focused on WNT5A protein at the tumour tissue level, less information is available on circulating ligands and their effects." (PMID 40223089, 2025). "In ESCC, HDAC7 can upregulate tumour progression mediated by WNT5A, regulate the expression of EMT-related molecules such as SNAIL and E-cadherin, and enhance the migration and invasion abilities of ESCC cells." (PMID 39990668, 2025). "In this context, particular attention should be paid to the study of β-catenin, which exhibits dual function, and context-dependent protein Wnt5a in various tumor microenvironments." (PMID 41465498, 2025). "The specific function of Wnt5a in the development of tumors is still not fully understood but it exhibits dual roles in cancer biology, functioning as a tumor suppressor in certain contexts and as a tumor promoter in others." (PMID 40373156, 2025). "Its interaction with FZD2 promotes cancer cell invasion, while suppression of ZEB1, a transcriptional regulator of Wnt5A, has been shown to reduce tumor cell proliferation and enhance apoptosis." (PMID 40943055, 2025). "Crucially, in vitro validation confirms that CTHRC1+ CAFs secrete WNT5A, which upregulates the mesothelin (MSLN) gene in CRC tumor cells - an effect abolished by WNT5A inhibition or CTHRC1 knockdown." (PMID 41450739, 2025). "Its highly context‐dependent roles in cancer (either tumor‐suppressive or tumor‐promoting) have been attributed to two distinct isoforms, WNT5a Short (WNT5aS) and WNT5a Long (WNT5aL), resulting from different signal peptide cleavage sites." (PMID 40165582, 2025).
tumor (continued). "The results of immunofluorescence staining confirmed the RES‐ and α‐MEL‐ and α‐MEL‐RES‐mediated effects on the regulation of β‐catenin and Wnt5a in the tumor tissues of orthotopic HS683‐Luc GB‐bearing nude mice." (PMID 40400263, 2025). "Wnt5a was expressed in the membranes and cytoplasm of tumor cells in 35 cases (47%), but was nearly undetectable in the non-neoplastic epithelium." (PMID 41008809, 2025). "LINC01134 sponges the tumor suppressor gene miR‐497‐5p and upregulates Wnt family member 5A (WNT5A) expression." (PMID 40448344, 2025). "By contrast, WNT5a is inactivated in other cancer types, such as hematological malignancies and colorectal carcinoma, suggesting tumor‐suppressive functions." (PMID 40165582, 2025). "While activation of the WNT5A pathway in tumor cells can promote tumor stemness and mediate chemotherapy resistance, our research focused mainly on the CXCL signaling pathway activated by IFN signaling in fibroblasts." (PMID 40319103, 2025). "Like other WNT ligands, WNT5a has been found on EVs, e.g., in the tumor microenvironment mediating invasiveness and activating profibrotic WNT signaling during cardiac fibrosis." (PMID 40165582, 2025). "When combined with low-dose DOX—a chemotherapy agent that induces ICD—the trapped Wnt5a-PNP system synergistically enhanced tumor antigen release and cross-presentation." (PMID 40861441, 2025). "Adding to this complexity, stromal-tumor crosstalk mediated by Wnt5a and hypoxia-induced fibroblasts (InfFib) establishes a pro-tumorigenic microenvironment in colorectal carcinoma." (PMID 41403952, 2025). "These metabolic adaptations sustain tumor survival and contribute to immune suppression, as seen in the Wnt5a-indoleamine 2,3-dioxygenase 1 (IDO1) axis, which fosters regulatory T-cell expansion and an immunosuppressive microenvironment." (PMID 40917745, 2025). "Desmoplastic and WNT5A+ inflammatory fibroblasts were indicated as the sources of tumor-enriched ECM proteins, while ADAMDEC1+ expressing fibroblasts and PI16+ expressing fibroblast were identified as the sources of NAT-enriched ECM proteins." (PMID 40032993, 2025). "The bone microenvironment undergoes further disruption due to tumor-derived Wnt ligands, such as Wnt1 and Wnt5a." (PMID 40426987, 2025). "Wnt5a exhibits dual roles in cancer biology, functioning as a tumor suppressor in certain contexts and as a tumor promoter in others." (PMID 40373156, 2025). "In many contexts, including the primary tumour setting investigated in this study, the Wnt5a/ROR2 axis is a potent driver of EMT, cytoskeletal rearrangement, and invasion." (PMID 41007281, 2025). "Mechanistically, these findings suggest that a population of Wnt5a high-expressing cells in the primary tumor likely drive focal adhesion formation to initiate cell migration and ultimately attachment at a distant location, contributing to metastases." (PMID 41301074, 2025). "Secreted WNT5A was suggested to interact with a wide range of tumor cell-expressing receptors, such as LRP5, LRP6, FZD5, and FZD6." (PMID 40524253, 2025). "More study is needed to fully understand the functional repercussions of these WNT5A genetic changes and their impact on tumor biology and the immune microenvironment." (PMID 39176352, 2024). "Depending on the biological environment and receptor expression, WNT5A can have tumor-suppressive and tumor-promoting actions." (PMID 39176352, 2024). "The analysis of WNT5A expression in different tumor types was conducted using the GEPIA and TIMER public databases." (PMID 39176352, 2024). "Tumor volume and weight were both elevated by CAFs, but silencing WNT5A in CAFs relieved this facilitation." (PMID 39054546, 2024). "This allowed us to unravel hallmark gene signatures of the tumor-normal ecosystems, outline distinctions between AKR1C1+ and WNT5A+ inflammatory fibroblasts, and characterize TLS-enriched and non-enriched cell types among immunotherapy-favorable components." (PMID 38744958, 2024).